MYC (MYC proto-oncogene, bHLH transcription factor)
Diseases named in the same sentence as MYC in open-access papers (continued):
Sharing a sentence is not in itself a finding about the gene and the disease.
tumor (continued). "More broadly, since immune cells are also rapidly-proliferating cells, they tend to share certain same pathways with tumor cells, such as MYC." (PMID 38243324, 2024). "PCa patients were divided into two cohorts of high MYC expression (n = 19) and low MYC expression (n = 19) based on the mean MYC IHC scores in tumor tissues." (PMID 38997648, 2024). "Differential gene expression analysis revealed upregulated genes in metastatic BM tumor cells related to E2F targets, oxidative phosphorylation, and mTORC1 signaling as well as MYC targets." (PMID 38358826, 2024). "As FGF19 tumor-promoting effects were observed in the context of cooperation with MYC or β-catenin, both of which have a documented pro-mitogenic activity, our result suggests that they are unlikely to be solely based on stimulation of cell proliferation." (PMID 38228803, 2024). "Among the samples with MYC copy number aberrations, only one synchronous tumor had MYC copy number amplification while MYC copy number gains were noted in the remaining synchronous and metachronous samples." (PMID 38939336, 2024). "Previous studies demonstrated that MYC inhibition modulates the tumor immune microenvironment and enhances anti-PD1 immunotherapy." (PMID 38169606, 2024). "A few studies have reported that hypusinated eIF5A promotes translation of RhoA and MYC in tumor cells." (PMID 38654332, 2024). "Conversely, WNT antagonists, tumor suppressors known to negatively regulate cell cycle, apoptosis and cell adhesion were downregulated in the MYC amplified disease." (PMID 38783041, 2024). "Given that MYC regulates the tumor microenvironment, in future studies, we will evaluate MYC synthetic lethal interactions in hosts with an intact immune system." (PMID 38302473, 2024). "Underscoring the multifaceted nature of this regulatory network, upon MYC inactivation, tumour regression is orchestrated by a combination of cell-autonomous processes and non-cell-autonomous mechanisms." (PMID 38637125, 2024). "When MYC-ON mice were starved of Trp, their livers retained a normal phenotype with a transcriptome more akin to the normal liver than tumor." (PMID 38769298, 2024). "As a primary downstream target of mTORC1 signaling, the 4EBP1/eIF4E cascade promotes c-MYC–driven HCC development by regulating tumor cell proliferation." (PMID 39325536, 2024). "On the other, overexpression of MYC initiates tumor-induced immune suppression through the crosstalk between tumor cells and different immune cell subsets in the TIME through the production of specific cytokines and chemokines." (PMID 39164274, 2024). "In fact, to date, the functions of RPs and MYC on tumor cells have been mostly studied separately, and laboratory investigations regarding their possible relationships in OS are lacking." (PMID 39596100, 2024). "Specifically, we enhanced the NCCN‐IPI with combinations of stromal FOXC1 and tumor pERK1‐2 as well as cell of origin, MYC/BCL2 double expression, and tumor pERK1‐2." (PMID 39404228, 2024). "In physiological conditions, Let-7 miRNAs function as tumor suppressor through transcriptional repression of key oncogenes, including MYC and RAS, by binding specific sites in the 5′-untranslated region (UTR) and activating the RNA-induced silencing complex." (PMID 39482742, 2024). "In vivo limiting dilution assays revealed that the loss of PCAT6 dramatically reduced tumor incidence, and reduced CD44+ breast CSCs, c‐MYC, and Ki67 were detected in PCAT6 knockdown cell‐formed xenografts compared with control xenografts." (PMID 38626369, 2024).
tumor (continued). "In summary, these results established that the MYC-degrading molecule A80.2HCl potentiates the therapeutic efficacy of CDK4/6i in inhibiting tumor growth, thereby providing an effective cancer treatment drug target for overcoming CDK4/6i resistance." (PMID 38424044, 2024). "MYC, as a typical tumor suppressor gene, has a wide range of gene expression regulation capabilities, and is currently used as a target for cancer treatment." (PMID 39877345, 2024). "In aggregate, these findings unravel a MYC-directed mechanism whereby tumor cells ensure balanced coordination of the production of ROS and the sanitation of nucleotide pools." (PMID 38493213, 2024). "In NSCLC cells, the CDK7 inhibitor THZ1 inhibits MYC transcriptional activity by downregulating p38α, thereby suppressing PD-L1 expression and improving the anti-tumor immunity against PD-1 therapy in vivo by recruiting infiltrating CD8+ T cells." (PMID 38762484, 2024). "In summary, due to the importance of MYC for coordinated expression of angiogenic factors required for tumor progression, disruption of MYC functions has potential to be effective for treating angiogenesis-dependent tumors." (PMID 37450923, 2024). "It was previously demonstrated that c-MYC represses the transcriptional activity of tumor- suppressive miRNAs such as the let-7 family." (PMID 38607000, 2024). "A second study examining mechanisms of tumor cell motility and invasion downstream of MYC identified MIRO2 as a target of MYC." (PMID 39128718, 2024). "In our model, the co-expression of FGF15 with MYC also gave rise to hepatic carcinogenesis, albeit within a slightly longer timeframe (7/8 mice exhibited tumors after 4–6 weeks post-HGT) and a lower tumor burden (mean = 10.3) in comparison with FGF19 + MYC." (PMID 38228803, 2024). "Targeting this loop with bromodomain and extraterminal (BET) inhibitors, by impairing the transcription of KLF16 and MYC, leads to reduced cell viability, tumor growth, and increased sensitivity to chemotherapy in BLCA." (PMID 39551759, 2024). "LMP2A has been shown to promote the hyperproliferation of B-cells by enhancing MYC expression and MYC-dependent degradation of the p27kip1 tumor suppressor." (PMID 39459858, 2024). "This indicates that due to the role of MYC in accelerating tumor progression, it further promotes tumor development." (PMID 38756785, 2024). "Targeting transcriptional CDKs is a viable option for TNBC because they have key features of transcriptionally addicted tumours, including overexpression or amplification of the MYC oncogene." (PMID 38001268, 2024). "Together, our data demonstrated that KMT2D mutations induced NOTCH-MYC activation, as well as MYC-dependent TGF-β1 secretion, and resulted in tumor induced-Treg cell trafficking." (PMID 39113693, 2024). "Biological hallmarks analysis demonstrates that OA tumours are significantly enriched in MYC targets compared to AYA tumours." (PMID 38762630, 2024). "MYC, on the other hand, is a well-established oncogene known to regulate several intrinsic tumor-cell mechanisms, to promote the survival, growth, and proliferation of tumor cells." (PMID 39766097, 2024).
tumor (continued). "Our results reveal the involvement of MYC in tumor escape from NK cell- and T cell-mediated cytotoxicity through diverse, non-overlapping mechanisms." (PMID 39596160, 2024). "As observed with RK‐33, MYCN‐amplified tumors were most susceptible to translation repression by ceftriaxone, followed by c‐MYC‐expressing tumor cells treated with high drug doses." (PMID 37975412, 2024). "Our results demonstrate that by inhibiting DHODH with brequinar, tumour cell growth and MYC levels are significantly reduced." (PMID 39766063, 2024). "We previously showed that, by inhibition of MYC, Omomyc can reprogram the tumor microenvironment through vascular remodeling and cytokine–chemokine modulation." (PMID 38321218, 2024). "Inducible activation of NFATC4 also resulted in the effective suppression of MYC expression in tumor cells." (PMID 38418814, 2024). "This plasticity is driven in part by MYC and Notch signaling, which promotes the dedifferentiation of tumor cells." (PMID 39850810, 2024). "MYC overexpression can facilitate the escape of cancerous or pre-cancerous cells from anti-tumor immune cell recognition; this escape iteration from immune responses is a hallmark of cancer." (PMID 37450923, 2024). "Herein, we compared the efficacy of ASO-AuNP conjugates to silence c-MYC oncogene in 2D cell models and 3D tumor spheroids." (PMID 38410164, 2024). "Studies of stemness genes in various tumor subtypes have revealed that MYC is significantly expressed in C0 FXYD5+ TCs, suggesting that this subtype has a high proliferative potential and is critical for tumor growth." (PMID 39717768, 2024). "Using both MYC-sgp53 and MYC-sgApc genotypes resulted in tumor formation with similar histological features to those of our non-Cre-restricted tumors, consistent with an epithelial and potentially parietal cell of origin in the EPO-GEMMs." (PMID 38177458, 2024). "Silencing c-MYC expression significantly reduced tumor burden in these mice supporting the necessity for c-MYC in tumor maintenance." (PMID 38352401, 2024). "MYC likewise can control the expression of the tumour-promoting factors: matrix metallopeptidase 9 (MMP9), VEGF, TGF-β and HIF-1 (Ref." (PMID 39320855, 2024). "The integrated Group 4 tumor datasets (n = 5) produced 9 clusters and represented 3 major groups: “MYC-driven,” “FSTL5-driven,” and “UBC-like” according to their transcriptional programs." (PMID 39659836, 2024). "This loop reinforces tumor stemness by stabilizing MYC and EP300 mRNAs via IGF2BP1‐mediated m6A modification." (PMID 39488785, 2024). "In the context of MYC-driven lymphomagenesis, the loss of IBTK primarily induces B-cell apoptosis and delays tumor onset." (PMID 38371626, 2024). "Molecularly, the anti-tumor effect of panobinostat is mediated by posttranslational obstruction of the MYC oncoprotein as a result of dual specificity phosphatase 1 upregulation, thereby leading to growth inhibition and programmed cell death." (PMID 39529166, 2024). "HCCs with high c-MYC activation displayed a markedly higher TSC1/2 mutation rate, suggesting the important role of TSC/mTORC1 during c-MYC tumor development." (PMID 39325536, 2024). "One pathway upregulated by MYC in the context of tumour growth and proliferation is that of pyrimidine synthesis." (PMID 39766063, 2024). "Unlike previous studies, our TMA-trained model can predict the proportion of positive tumor cells in c-MYC- and BCL2-stained WSIs." (PMID 38243330, 2024). "Some of these ubiquitination events are opposed by the activity of the deubiquitinase (DUB) USP28; for example, c‐MYC stability in human tumour cells is USP28 dependent and USP28 binds to MYC through a nuclear interaction with FBW7α." (PMID 37866880, 2024). "In our study, we reveal the interplay of MYC and DHODH in group 3 MB, based on the group-specific expression of DHODH in MB tumours, and discover the sustained inhibition of MYC expression upon BRQ single-dose treatment in two human MB cell lines." (PMID 39766063, 2024).
tumor (continued). "By contrast, monoclonal tumours were enriched in expression of targets of MYC compared to both major and minor clones." (PMID 39478206, 2024). "NPAS2, with BMAL1, regulates the MYC promoter, influencing cell cycle dynamics and potentially affecting tumour growth." (PMID 39566400, 2024). "Our results further showed that as single agents, both MP1 and temsirolimus, were able to significantly inhibit tumor growth and MYC expression in subcutaneously or orthotopically MYC-amplified MB bearing mice." (PMID 38200580, 2024). "Although the mechanisms by which triptolide and its analogs arrest tumor growth are not fully understood, MYC levels seem to predict sensitivity to triptolide, with those tumors harboring MYC amplifications showing the greatest sensitivity." (PMID 38885332, 2024). "Several groups have shown that high MYC levels can alter glutamine metabolism in cancer, and sensitize tumor cells to therapies targeting glutamine." (PMID 39337668, 2024). "In line with the immunosuppressive role of MYC in the tumor immune microenvironment, several immune-related gene sets were upregulated following its inhibition by OMO-103, especially those related to T cell-mediated immunity." (PMID 38321218, 2024). "FBXW7 functions as a tumor suppressor gene by regulating the degradation of oncoproteins, such as c-MYC, suggesting a tumor-suppressive role of m6A specifically in this cellular context." (PMID 38444581, 2024). "In cancer, the tumor often exploits the expression and activity of the MYC oncogene, resulting in elevated levels of MYC mRNA and protein." (PMID 39596100, 2024). "As bowel epithelium transforms, MYC is often expressed by various mechanisms that initiate and/or sustain tumor growth." (PMID 38637125, 2024). "Studies reported that prolonged tumor regression was achieved in wild-type animals through the suppression of MYC and several other oncogenes in GE conditional mouse models of lymphoma/leukemia." (PMID 38473324, 2024). "The unique tumor-driver networks and enhancer-hijacking events correlated with MYC activation were identified in TCP-like cells, pointing to the putative cellular origin of group 3 MBs and the potential therapeutic avenues." (PMID 38355808, 2024). "In summary, there is compelling evidence indicating that the neutralization of the charge polarity within the E242-E261 of the MYC segment facilitates the formation of pathological MYC aggregates, thereby accelerating tumor growth." (PMID 39343006, 2024). "This suggests that while targeting MYC to control tumor growth is a viable strategy, it must be approached with caution due to the potential risk of promoting metastasis." (PMID 39883338, 2024). "The m6A reader IGF2BP1 stabilizes the EP300 and MYC mRNAs by recognizing m6A modifications, forming a positive feedback loop that enhances tumor stemness and ultimately contributes to PDAC resistance." (PMID 39488785, 2024). "Contrary to the role of MYC in promoting tumor cell migration, one study found that MYC can suppress cell migration." (PMID 37450923, 2024). "The MYC locus is a tumor type-specific super-enhancer that expresses different super-enhancer-derived ncRNAs." (PMID 38763947, 2024). "mTOR signaling pathway can normally activate GLUT1, a key glycolysis protein, which can enhance the Warburg effect of tumor cells through the transcription factors HIF1α and MYC." (PMID 39003253, 2024). "High-lactate TMEs can promote c-MYC activation in tumor cells, enhancing cell proliferation, promoting L-glutamine uptake, and impairing anti-tumor immune cell function by competing for L-glutamine." (PMID 39227970, 2024).
tumor (continued). "Brat in Drosophila brains, and TRIM3 in GBM cells, supress MYC expression, and MYC inhibition reduces both brat tumour growth and GSC tumourigenic potential in vitro and when xenotransplanted in mice." (PMID 38225354, 2024). "Our in vivo results further confirm this synergy in reducing tumor growth and prolonging survival in subcutaneously or orthotopically MYC-driven MB bearing mice." (PMID 38200580, 2024). "Novel in vivo models incorporating the human immune system and engrafted with patient-derived tumor xenografts probably face challenges with high toxicity induced by direct MYC inhibitors." (PMID 39596160, 2024). "Deactivating MYC was found to reverse this reprogramming and reinstate normal anti-tumor immune function." (PMID 38390324, 2024). "Upon examining how KRAS mutations and MYC dysregulation tailor the TIME and impact different immune populations in several tumor types, it is apparent that they share several mechanisms." (PMID 39164274, 2024). "This study assessed ASO-AuNP conjugates for silencing the c-MYC oncogene in 2D cultures and 3D tumor spheroids, revealing distinctions in gene silencing efficiency and highlighting the microenvironment’s impact on AuNP-mediated gene modulation." (PMID 38410164, 2024). "Studies have also elucidated that LINRIS inhibits IGF2BP2 degradation in CRC HCT116 cells by inhibiting K139 ubiquitination, thereby promoting downstream MYC‐mediated glycolysis and tumor proliferation." (PMID 38721006, 2024). "In SCLC, MYC activated Notch to dedifferentiate neuroendocrine (NE) tumor cells and promoted the temporal evolution of SCLC from ASCL1+ state to NEUROD1+ state to YAP1+ state." (PMID 39723215, 2024). "HDAC inhibition, in combination with the novel MYC inhibitor, inhibited oncogenic transcriptional signatures and reduced tumor growth in vivo." (PMID 39093942, 2024). "Compared to wildtype USP28, monomeric USP28 had a stronger stabilizing effect on MYC in HLF cells and in a p19Arf-deficient, Nras-transformed murine HCC cell line established from an autochthonous tumor (p19-/-Nras)." (PMID 38227944, 2024). "Taken together, these findings highlight the critical role of XPO1-mediated nuclear to cytoplasmic transport in promoting MYC-driven tumor growth." (PMID 38302473, 2024). "Depletion of JMJD6 inhibits cancer cell proliferation and impedes tumor growth while overexpression of JMJD6 promotes MYC-mediated tumorigenesis, suggesting that JMJD6 and potentially other 17q genes have oncogenic functions in cellular transformation." (PMID 38488852, 2024). "Fortunately, scientists have developed MYC inhibitors which can inhibit tumor growth in mice and increase tumor immune cell infiltration." (PMID 39470950, 2024). "Both subtypes showed a “transcriptional/translational” profile and a high abundance of MYC target proteins along with a high fraction of MYC-positive tumor cell nuclei." (PMID 39043693, 2024). "MLN4924 showed several side effects including tumor sphere formation and ciliogenesis inhibition through the c-MYC accumulation and dimerization of EGFR, activating the EGFR signaling pathway." (PMID 38398217, 2024). "Such genes should reveal processes that help tumor cells adapt to and thrive on MYC-driven metabolic reprogramming." (PMID 38493213, 2024). "It is interesting to note that while exogenous expression of NR2F6 following circMIRO1 depletion in HCC xenograft models fully rescued tumor growth, exogenous expression of c-MYC had only a partial rescue of tumor growth in NSCLC xenograft models." (PMID 39128718, 2024).